MC5R (melanocortin 5 receptor)
Description:
G protein-coupled receptor for melanocyte-stimulating hormones (alpha-beta- and gamma-MSH) and corticotropin/ACTH, which are peptide products of the POMC precursor. Upon activation, couples to G(s) protein, stimulating adenylate cyclase and the cAMP-dependent signaling pathway. Also activates ERK1/2 via a PI3K-dependent signaling mechanism. Order of potency of natural melanocortins in receptor activation is alpha-MSH > ACTH > beta-MSH > gamma-MSH. Plays a key role in immune response, and is essential for temperature regulation and exocrine gland function (By similarity).
Synonyms: MC2
Tractability: Small molecule: a high-quality ligand is known; it belongs to a druggable protein family. Antibody: its Gene Ontology location is reachable by antibodies, with high confidence; UniProt places it where antibodies can reach, with medium confidence; UniProt predicts a signal peptide or a membrane-spanning region; the Human Protein Atlas places it where antibodies can reach. PROTAC: a small molecule that binds it is known.
Target class: Short peptide receptor (family A GPCR); Peptide receptor (family A GPCR); Melanocortin receptor; Membrane receptor; Family A G protein-coupled receptor
Chemical probes: CHEMBL220018, CHEMBL2371968
Gene: Protein-coding gene on chromosome 18 (13,824,149 to 13,827,323, forward strand). Ensembl gene ENSG00000176136.
Subcellular location: Cell membrane
Subcellular location (Human Protein Atlas): Plasma membrane
Pathways (Reactome):
Signal Transduction: G alpha (s) signalling events; Peptide ligand-binding receptors
Developmental Biology: Transcriptional and post-translational regulation of MITF-M expression and activity
Gene Ontology:
Molecular function: melanocyte-stimulating hormone receptor activity; protein binding; corticotropin receptor activity; melanocortin receptor activity; G protein-coupled receptor activity; hormone binding
Biological process: adenylate cyclase-activating G protein-coupled receptor signaling pathway; positive regulation of ERK1 and ERK2 cascade; G protein-coupled receptor signaling pathway, coupled to cyclic nucleotide second messenger; negative regulation of immune response; positive regulation of exocytosis; signal transduction; temperature homeostasis; G protein-coupled receptor signaling pathway; neuropeptide signaling pathway
Cellular component: plasma membrane; cytoplasm; membrane
Genetic constraint (gnomAD): Loss-of-function variants: 0 observed, 0.28 expected, observed/expected ratio (o/e) 0, 90% interval 0 to 1.87. That is too few expected variants to judge how well the gene tolerates losing a copy. Missense variants: 420 observed, 457.73 expected, observed/expected ratio (o/e) 0.92, 90% interval 0.85 to 1. Synonymous variants: 167 observed, 175.65 expected, observed/expected ratio (o/e) 0.95, 90% interval 0.84 to 1.08.
Homologues: Orthologues: macaque MC5R (93% identical), rabbit MC5R (90% identical), dog MC5R (86% identical), guinea pig MC5R (83% identical), rat Mc5r (81% identical), mouse Mc5r (80% identical), tropical clawed frog mc5r (77% identical), pig MC5R (75% identical), zebrafish mc5ra (70% identical), zebrafish mc5rb (68% identical). Paralogues in human: MC4R (62% identical), MC3R (59% identical), MC1R (43% identical), MC2R (42% identical), S1PR1 (26% identical), LPAR1 (26% identical), GPR12 (26% identical), S1PR3 (25% identical), LPAR2 (25% identical), GPR3 (24% identical), GPR6 (24% identical), S1PR2 (23% identical), and 6 more.